SFSWAP (splicing factor SWAP)
Description:
Plays a role as an alternative splicing regulator. Regulate its own expression at the level of RNA processing. Also regulates the splicing of fibronectin and CD45 genes. May act, at least in part, by interaction with other R/S-containing splicing factors. Represses the splicing of MAPT/Tau exon 10.
Synonyms: SFRS8; SWAP
Tractability: Antibody: the Human Protein Atlas places it where antibodies can reach. PROTAC: ubiquitination databases record sites on it; its protein half-life has been measured.
Gene: Protein-coding gene on chromosome 12 (131,711,081 to 131,799,738, forward strand). Ensembl gene ENSG00000061936.
Subcellular location: Nucleus
Subcellular location (Human Protein Atlas): Nucleoplasm; Cytosol; Plasma membrane
Gene Ontology:
Molecular function: protein binding; RNA binding
Biological process: mRNA 5'-splice site recognition; negative regulation of mRNA splicing, via spliceosome; RNA processing
Cellular component: nucleus
Genetic constraint (gnomAD): Loss-of-function variants: 14 observed, 91.04 expected, observed/expected ratio (o/e) 0.15, 90% interval 0.1 to 0.24. The upper end of that interval is the gene's LOEUF score, 0.24, which puts it in group 1 of 6, group 1 being the genes least tolerant of losing a copy. Missense variants: 960 observed, 1,230.2 expected, observed/expected ratio (o/e) 0.78, 90% interval 0.74 to 0.82. Synonymous variants: 484 observed, 500.72 expected, observed/expected ratio (o/e) 0.97, 90% interval 0.9 to 1.04.
Homologues: Orthologues: chimpanzee SFSWAP (99% identical), macaque SFSWAP (97% identical), guinea pig SFSWAP (91% identical), pig SFSWAP (90% identical), dog SFSWAP (89% identical), rabbit SFSWAP (89% identical), rat Sfswap (89% identical), mouse Sfswap (89% identical), tropical clawed frog sfswap (64% identical), zebrafish sfswap (60% identical), Drosophila melanogaster su(w[a]) (29% identical). Paralogues in human: CLASRP (16% identical).
Diseases named in the same sentence as SFSWAP in open-access papers:
SFSWAP is named in the same sentence as 12 diseases in open-access papers, as found by Europe PMC text mining. Sharing a sentence is not in itself a finding about the gene and the disease. The quoted sentences say what the papers report.
autosomal dominant deafness (1 paper, 2014). "In humans, the nonsyndromic autosomal dominant deafness locus DFNA41 contains at least 100 genes, including SFSWAP." (PMID 24391519, 2014).
colon cancer (1 paper, 2022). "As a potential splicing factor, SFSWAP can alternatively regulate gene expression, and the cg09170112 methylation site of SFSWAP has been verified to be significantly correlated with colon cancer prognosis." (PMID 36100894, 2022).
osteoporosis (1 paper, 2023). A condition of reduced bone mass, with decreased cortical thickness and a decrease in the number and size of the trabeculae of cancellous bone (but normal chemical composition), resulting in increased fracture incidence. "In addition, considering that both Notch pathway and Jagged1 gene are associated with SfSWAP, this may indicate the potential role of SFSWAP in the development of osteoporosis." (PMID 38260098, 2023).
sarcoidosis (1 paper, 2024). Sarcoidosis is a multisystemic disorder of unknown cause characterized by the formation of immune granulomas in involved organs. "Our integrated model also demonstrated differential expression/methylation of IL20RB, ABCC11, SFSWAP, AGBL4, miR-146a-3p, and miR-378b between non-progressive and progressive sarcoidosis." (PMID 39080656, 2024).
systemic hypertension (1 paper, 2022). "Interestingly, SLC38A2, a calcium transporter that shows a significant increase in both mRNA and protein and splicing factor, and the suppressor of white-apricot homolog (SFSWAP), which is increased in protein expression analysis, are implicated in systemic hypertension." (PMID 36176278, 2022).
infection (1 paper, 2018). The state of being infected such as from the introduction of a foreign agent such as serum, vaccine, antigenic substance or organism. "Since only two transcripts (SFSWAP and CRAMP1) were found downregulated at 6-weeks post-infection, GO analysis did not result in any term overrepresented." (PMID 29615760, 2018).
SFSWAP also shares sentences with these, for which no sentence is quoted: acute myeloid leukemia (1 paper); breast carcinoma (1); cancer (1); monoclonal gammopathy of undetermined significance (1); multiple myeloma (1); tumours (1).